IL13 (interleukin 13)
Diseases named in the same sentence as IL13 in open-access papers (continued):
Sharing a sentence is not in itself a finding about the gene and the disease.
allergic asthma (continued). "Th2 cytokines, including IL‐4, IL‐5, and IL‐13, are important factors in the pathophysiological characteristics of allergic asthma." (PMID 35344278, 2022). "Here, we showed that our model of MAA recapitulates the exposure to cytokines that are hallmarks of the allergic asthma response, including increased levels of IL-4, IL-6, IL-5, IL-13, and IL-17." (PMID 36009104, 2022). "The Th2 polarization is characterized by IL-4/IL-13 dependent pathway activation in atopic eczema, allergic asthma, and food allergies and consistently we observed similar and significantly higher values of these cytokines." (PMID 35458127, 2022). "Six of the hub genes were markedly elevated in murine asthmatic lungs and were positively associated with IL-5, IL-13 and MUC5AC, which are the key mediators of allergic asthma." (PMID 36211429, 2022). "IL-13, a T helper type 2 cytokine, demonstrated the ability to regulate most of pathological processes in allergic asthma." (PMID 33628848, 2021). "Specifically, IFNG, IL-13, IL-5, and IL-4R showed an especially high overall relationship with allergic conditions (respiratory allergy and allergic asthma)." (PMID 33936056, 2021). "For example, a human anti‐IL‐4Rα monoclonal antibody which interrupts signaling of both IL‐4 and IL‐13 has demonstrated convincing efficacy in controlling moderate‐to‐severe atopic dermatitis, allergic asthma, and nasal polyps." (PMID 34429871, 2021). "We show that prophylactic and therapeutic dual vaccination against mouse IL-4 and IL-13 reduces key features of chronic allergic asthma in mice." (PMID 33976140, 2021). "Overall, our results suggest that dual IL-4/IL-13 vaccination is a promising long-term therapeutic strategy for allergic asthma, pending further safety and feasibility assessment in additional preclinical models." (PMID 33976140, 2021). "As IL13 is a validated target in driving the allergic asthma phenotype, IL13 neutralization had attractive therapeutic potential." (PMID 33918602, 2021). "More over eosinophils play important roles in augmenting AHR, mucus production, and airway remodeling in allergic asthma by producing IL-13 and leukotrienes from eosinophil lipid bodies." (PMID 34366865, 2021). "Airway inflammation, mucus hypersecretion, and airway hyperresponsiveness (AHR) are the major symptoms of allergic asthma and are profoundly impacted by Th2 cytokines, such as IL-4, IL-5, and IL-13, and chemokines." (PMID 33919784, 2021). "Evidence states that IL-4, IL-5, and IL-13 drive allergic asthma, which explains the importance of these molecules as drug targets in the management of T2 high allergic asthma." (PMID 34572281, 2021). "This study has demonstrated that the production of periostin is initiated by IL-13, a Type 2 cytokine with well-known roles in allergic asthma." (PMID 35387027, 2021). "IL-4 and IL-13 cause M2 macrophages to express TGF-β, which, in turn, induces the proliferation of airway smooth muscle cells, fibrosis, and airway remodeling in allergic asthma." (PMID 33919784, 2021). "Th2-mediated allergic responses to fungal in mice, resulting in repeated lung exposure to fungal strains, produce IL-4 and IL-13 as well as the intratracheal direction of fungal spores induced allergic asthma in mice." (PMID 33413198, 2021). "CHI3L1 is known to promote type 2 immune responses such as those that are seen in allergic asthma, and IL-13 plays a key role in these responses." (PMID 34747367, 2021). "OXY significantly ameliorates allergic asthma by suppressing T-cell response including down regulation of IL-4, IL-5, and IL-13 expression levels." (PMID 33946346, 2021). "IL-13 overexpression was found to be sufficient enough to induce most of the features of allergic asthma seen in human patients in other murine models of allergen challenge." (PMID 33628848, 2021).
allergic asthma (continued). "The activated T lymphocytes then produce several pro-inflammatory cytokines such as interleukin (IL) IL-4, IL-5, IL-9, IL-13, and GM-CSF that are major components of the inflammatory response in AR as well as allergic asthma." (PMID 34638811, 2021). "Another surprising finding about IL-10 role in allergic asthma, is the induction of airway fibrosis through IL-13/STAT6 pathway or increased TGF-β production, with mucus hypersecretion." (PMID 32024540, 2020). "In allergic asthma airway epithelial cells are one of the main producers of proinflammatory cytokines and chemokines like IL-13, IL-33, TSLP, CCL5 (Rantes), CCL7 (MCP-3), CCL17 (TARC), CCL22, and several eotaxins." (PMID 32411147, 2020). "Similar to the case in the mRNA expression level of IL-5 and IL-13 in allergic asthma, the percentages of IL-5+ and IL-13+ CD4+ Th cells were significantly lower in HDM-sensitized Tlr9−/− mice than in HDM-sensitized WT mice." (PMID 33093516, 2020). "Th2-type cytokines such as IL-4, IL-5, and IL-13 play a vital role in the progression of the allergic asthma." (PMID 32617136, 2020). "Th2 type cytokines (e.g. interleukin (IL)-4, IL-5, and IL-13) play a major role in the pathogenesis of allergic asthma." (PMID 32600285, 2020). "Kaempferol, one of the principal constituents in S. nigra, has its therapeutic implications in the treatment of allergic asthma by inhibiting IL-4, IL-5, and IL-13 secretion." (PMID 32617136, 2020). "The Th2 cytokines that play an important role in allergic asthma, like IL-5, IL-13, CCL17, and IL-33 along with total IgE in serum were measured." (PMID 32582180, 2020). "Comprehensive studies of targeted and inducible pulmonary overexpression of IL-13 in TG mice have defined the role of IL-13 in the cellular and molecular responses to allergic asthma." (PMID 33046682, 2020). "The type 2 cytokines, interleukin- (IL-) 4, IL-5, IL-9, and IL-13, are the major drivers of allergic asthma and studies." (PMID 31737687, 2019). "Despite these similarities, a number of in vivo functional experiments have shown that IL-4 and IL-13 facilitate different features of allergic asthma." (PMID 31340811, 2019). "Bronchial inflammation, smooth muscle spasm, and mucus production in allergic asthma are triggered by IL-4, IL-5, and IL-13, which are released by Th2 cells." (PMID 31637021, 2019). "Cytokines such as IL-4, IL-5, and IL-13 have a close relation with the phenotype of allergic asthma." (PMID 30783201, 2019). "It is accepted that increased productions of some cytokines such as IL-4, IL-5 and IL-13 play vital roles in the inflammatory mechanism of allergic asthma." (PMID 31223464, 2019). "Controlling Th2-mediated responses (i.e., the production of IL-4, IL-5, and IL-13) can have a potential therapeutic role in allergic asthma." (PMID 31637021, 2019). "Especially, IL-25 protein in the lung were upregulated by inhaled as compared to intranasal OVA challenge with increased IL-13 protein in OVA-induced allergic asthma." (PMID 31823765, 2019). "Like Th2 cells, ILC2s secrete IL-5 and IL-13 and participate in processes such as antihelminth infection, tissue repair after influenza virus infection, and allergic asthma." (PMID 31320835, 2019). "Seminal studies in animal models of allergic asthma demonstrated that selective neutralization of IL-13 reduced airway hypersensitivity (AHR), bronchoalveolar lavage (BAL) eosinophils, and mucus overproduction." (PMID 31866859, 2019). "Results revealed that thymol effectively reduced the symptoms of allergic asthma through dose-dependent inhibition of IL-4, IL-5 and IL-13 production at 4, 8 and 16 mg/kg in OVA-challenged mice." (PMID 31275149, 2019). "Within the pollen season, a positive correlation between the percentages of circulating IL-13+ILC2s and FeNO levels was observed in patients with pollen-allergic asthma (r = 0.8785, P < 0.001)." (PMID 29449864, 2018).
allergic asthma (continued). "Allergic asthma is mediated by activated TH-2 cells promoting lung inflammation by secretion of key cytokines such as IL-4, IL-5, and IL-13." (PMID 30500834, 2018). "Although, IL-4 and IL-13 share a functional receptor complex (IL-4Rα/IL-13Rα1), they possess distinct roles in mediating allergic asthma in vivo." (PMID 30233597, 2018). "For example, differences in H3ac and H4ac levels at the interleukin 13 (IL-13) gene (IL13) that were observed in CD4+ T-cells from children with allergic asthma and healthy controls correlated with serum IL-13 concentrations." (PMID 29796022, 2018). "Most of the mechanistic understanding of IL-13 was gained in in-vitro and in-vivo animal models of allergic asthma." (PMID 30500834, 2018). "Abundant evidence from both human and animal studies has shown that the Th2 cytokine IL-13 plays a central role in directing the immune response to an allergic asthma phenotype." (PMID 28704401, 2017). "Its production is stimulated early in the allergic asthma cascade by the release of IL-4, IL-5, and IL-13 through activated Th2 cells." (PMID 29176991, 2017). "On its own, IL-13 is sufficient to induce some of the main characteristics of allergic asthma, i.e. airway hyperreactivity (AHR), airway inflammation via eosinophil recruitment, mucus production by airway epithelial cells and sub-epithelial fibrosis." (PMID 28704401, 2017). "Th2 cells then mediate the allergic asthma pathway through proinflammatory cytokines—i.e., interleukins (IL)-4, IL-5, IL-9, and IL-13—leading to the production of immunoglobulin E (IgE) early in the cascade and, later, eosinophils." (PMID 29176991, 2017). "The importance of IL-13 in classic allergic asthma has thus been identified in both human and animal studies." (PMID 28704401, 2017). "IL-13 is a key Th2 cytokine that directs many of the important features of airway inflammation and remodelling in patients with allergic asthma." (PMID 28057889, 2017). "More recently, IL-25 and IL-33 promote the population expansion of IL-5- and IL-13-producing ILC2s that have been shown to promote pathogenesis in mouse models of allergic asthma and atopic dermatitis." (PMID 27378934, 2016). "In the allergic asthma model, the Th2 cytokines, such as IL-4, IL-5, and IL-13, were clearly increased in the lung tissues." (PMID 27669297, 2016). "Murine studies have shown that ILC2s accumulated in the lung and significantly contributed to IL-5 and IL-13 production in allergic asthma." (PMID 27547445, 2016). "In typical Th2-type allergic asthma, interleukin (IL)-4 and IL-13 predominate, driving IgE production and recruitment of eosinophils into the lungs." (PMID 26635789, 2015). "IL-4 and IL-13 are two such cytokines that have been shown to play a central role in directing the pathophysiological changes in allergic asthma." (PMID 26362930, 2015). "In the present study we used a sheep model of allergic asthma to investigate the kinetics of expression of IL-4 and IL-13 in allergen-challenged airways, with the goal to extend our understanding of Th2-driven mechanisms in this large animal model system." (PMID 26362930, 2015). "Allergic asthma is another prototypical Th2 cytokine-driven disease which strongly instructs E-cadherin expression in M(IL-4/IL-13) macrophages." (PMID 26226941, 2015). "We found that T-bet-/- mice exposed to NiNPs had exaggerated airway mucous cell metaplasia, higher levels of mucin gene mRNAs, and increased levels of IL-13 and CCL2, two cytokines implicated in allergic asthma." (PMID 24499286, 2014). "Th2 cells are critical for the induction of allergic asthma via production of IL-4, IL-5, IL-13, and eotaxin." (PMID 24658532, 2014). "Allergic asthma is primarily mediated by Th2 cells, which secrete the characteristic cytokines IL-4, IL-5, and IL-13." (PMID 24955743, 2014).
allergic asthma (continued). "Taken together, our results demonstrate possible therapeutic potentials of sesamin in reducing the TH2 immune reaction sand the following inflammatory response mediated by IL-4, IL-5, and IL-13 in human allergic asthma." (PMID 24755955, 2014). "Th2 cytokines including IL-4, IL-5, and IL-13 have been shown to play crucial roles in the regulation of pulmonary inflammatory responses in allergic asthma." (PMID 25415454, 2014). "IL-4 and IL-13 are key Th2 cytokines that direct many of the important features of airway inflammation and remodeling in patients with allergic asthma." (PMID 24204835, 2013). "Among these Th2 cytokines, IL-13 has been demonstrated to be a critical mediator in the mucus obstruction phenotype evidenced in the mouse model of allergic asthma." (PMID 24367979, 2013). "A recent study showed that neutralization of IL-13 reduced airway inflammation, improved baseline lung function and inhibited airway remodeling in a mouse model of allergic asthma." (PMID 23300949, 2013). "It is well known that overexpression of GATA-3 predisposes for Th2-mediated diseases such as allergic asthma and suppression of GATA-3 expression in the lung reduces IL-4, IL-5, and IL-13 productions concurrently." (PMID 23800145, 2013). "It was reported that eosinophils, Th2 lymphocytes and their released inflammatory mediators, such as IL-5 and IL-13, played a crucial role in human allergic asthma." (PMID 23731974, 2013). "T helper 2 (Th2) cytokines, including IL-4, IL-5 and IL-13, predominate primarily in mild to moderate allergic asthma." (PMID 24204835, 2013). "In the present study, ST36 EA stimulation suppressed the increased antigen-specific IgE production and Th2 cytokines such as IL-4, IL-5, and IL-13 in OVA-induced allergic asthma mice." (PMID 22649477, 2012). "IL-13 is an important cytokine in airway hyperresponsiveness, mucus production, airway remodeling, subepithelial airway fibrosis, infectious asthma, allergic asthma, and aspirin exacerbated respiratory disease." (PMID 23283176, 2011). "Accordingly, IL-13, which is produced by Th2 cells and known to be a critical mediator of allergic asthma, was decreased by rIL-22 in a dose dependent manner." (PMID 21789181, 2011). "Antibody blockade of IL-13 in mouse lungs challenged with Aspergillus fumigatus conidia, to simulate chronic allergic asthma, or bleomycin, to simulate toxin mediated fibrosis, led to decreased lung collagen deposition." (PMID 23283176, 2011). "In a mouse model of ragweed pollen extract (RWE)-induced allergic asthma treatment with fidarestat prevented the expression of IL-13, phosphorylation of STAT-6 and transformation of epithelial cells to goblet cells in the lung." (PMID 21203431, 2010). "IL-13 is thought to be a critical mediator of allergic asthma, with genetic and pharmacological evidence supporting its involvement in the development of airway hyperreactivity (AHR) and the development of chronic asthma and remodeling phenotypes." (PMID 20573261, 2010). "IL-13 is also an important cytokine mediator of allergic asthma and is responsible for regulating eosinophilic inflammation, mucus secretion, and airway hyperresponsiveness." (PMID 19478971, 2009). "In allergic asthma, IL-13 is well established as an inducer of airway inflammation and tissue remodeling." (PMID 17620132, 2007). "IL‐4 and IL‐13, which share the Type 2 receptor IL‐4R, play a crucial role in the pathogenesis of airway hyperresponsiveness, goblet cell metaplasia, and increased production of airway mucus in patients suffering from allergic asthma." (PMID 41568067, 2026). "We therefore set out to determine whether mucins could cause eosinophil degranulation, by culturing human eosinophils in mucus secreted by human airway epithelial cells (HAECs) stimulated with IL-13 to recapitulate an allergic asthma environment." (PMID 40091838, 2025).
allergic asthma (continued). "Furthermore, patients with non-allergic asthma also had lower IL-13 levels than patients with sarcoidosis (p = 0.03)." (PMID 40725075, 2025). "Firstly, this study observed that the activity of peripheral blood Th1 cytokines (such as IL-2, IFN-γ) was significantly reduced, while the activity of Th2 cytokines (such as IL-4, IL-13) was significantly enhanced in children with acute exacerbations of allergic asthma." (PMID 40260311, 2025). "However, IL-13 is known to contribute to the pathology of allergic asthma and thus systemic administration should be avoided." (PMID 40822305, 2025). "In addition, patients with allergic asthma also develop type 2 immune responses, resulting in an increased production of cytokines such as interleukin-13, which significantly decreases ACE2 gene expression." (PMID 38961350, 2024). "Finding IL-13-mediated regulation of P2ry2 receptors has important implications for future preclinical studies since these receptors promote mucin secretion in response to ATP and are considered pro-inflammatory in allergic asthma models." (PMID 38711951, 2024). "Th2 allergic asthma is associated with many markers of type 2 inflammation, notably high levels of interleukin-13 (IL-13)." (PMID 38706568, 2024). "IgE and IL-13 play major roles in the regulation of inflammation in allergic asthma." (PMID 39769348, 2024). "OVA-induced allergic asthma increased the levels of Inf-γ (Th1 cytokine), Il-4 and Il-13 (Th2 cytokines), and Il-17a (Th17 cytokine) mRNAs in BALF cells, whereas the administration of empagliflozin or canagliflozin administration reduced the extent of these increases." (PMID 39062810, 2024). "In recent years, several biologic antibodies have been clinically introduced such as omalizumab (anti-IgE), dupilumab (anti-IL-4), and mepolizumab (anti-IL-5), because IgE and Th2 cytokines (IL-4, IL-5, and IL-13) play crucial roles in allergic asthma pathogenesis." (PMID 39062810, 2024). "Allergic asthma is generally classified as an eosinophilic airway disorder, and previous studies have focused on the role of Th2 cells and type 2 cytokines, including IL-4, IL-5, and IL-13." (PMID 38790633, 2024). "Since allergic asthma is associated with the presence of IL-13-producing cells in bronchoalveolar lavage (BAL) and plays a relevant role in the development of the disease, we decided to study the IL13 gene expression in our model by using qPCR." (PMID 36089628, 2023). "As IL-13 is involved in IgE production in allergic asthma patients in atopic diseases, we discuss that atopic patients with likely elevated IgE may suffer from an aggravation in post-viral immune dysregulation that in turn leads to persistent phenotypes." (PMID 37892261, 2023). "SUMF2 is a member of the formylglycine-generating enzyme family and may mediate airway inflammation in allergic asthma by regulating IL-13 expression." (PMID 37168863, 2023). "Airway hyperreactivity was induced in allergic asthma by IL-13, a key TH2 cytokine." (PMID 37443808, 2023). "Elevated gene expression levels of IL-4 and IL-13, detected in our study, might explain the development of long-term allergic asthma often observed in humans after prolonged exposure to welding fumes or ZnO inhalation." (PMID 38097754, 2023). "The increased levels of IL-4 and IL-13 cytokines may explain the development of long-term allergic asthma after exposure to ZnO nanoparticles, which is well-known among welders, smelters, and metal workers." (PMID 38097754, 2023). "Th2 cytokines, such as IL-13 play a major role in the progression of allergic asthma." (PMID 36077141, 2022). "The unbalance of Th1/Th2 cells response in allergic asthma shows that the IL-4, IL-5, and IL-13 and its respective transcription factor STAT6 remains intensely upregulated at the expense of a drastic decrease of T-bet levels in the airway of individuals with allergic asthma." (PMID 36685604, 2022).